CCNY (cyclin Y)
Description:
Positive regulatory subunit of the cyclin-dependent kinases CDK14/PFTK1 and CDK16. Acts as a cell-cycle regulator of Wnt signaling pathway during G2/M phase by recruiting CDK14/PFTK1 to the plasma membrane and promoting phosphorylation of LRP6, leading to the activation of the Wnt signaling pathway. Recruits CDK16 to the plasma membrane. Isoform 3 might play a role in the activation of MYC-mediated transcription.
Synonyms: C10orf9; CBCP1; CFP1; CCNX
Tractability: Small molecule: a high-quality ligand is known. Antibody: UniProt places it where antibodies can reach, with high confidence; its Gene Ontology location is reachable by antibodies, with high confidence. PROTAC: UniProt records ubiquitination sites on it; ubiquitination databases record sites on it; its protein half-life has been measured.
Gene: Protein-coding gene on chromosome 10 (35,247,025 to 35,572,669, forward strand). Ensembl gene ENSG00000108100.
Subcellular location: Cell membrane; Nucleus (Isoform 3)
Subcellular location (Human Protein Atlas): Nucleoplasm; Nucleoli
Gene Ontology:
Molecular function: cyclin-dependent protein serine/threonine kinase regulator activity; protein binding; cyclin-dependent protein serine/threonine kinase activator activity; protein kinase binding
Biological process: G2/M transition of mitotic cell cycle; positive regulation of autophagy; positive regulation of cyclin-dependent protein serine/threonine kinase activity; regulation of canonical Wnt signaling pathway; spermatogenesis
Cellular component: cyclin-dependent protein kinase holoenzyme complex; cytoplasmic cyclin-dependent protein kinase holoenzyme complex; nucleolus; nucleoplasm; nucleus; plasma membrane
Genetic constraint (gnomAD): Loss-of-function variants: 14 observed, 28.76 expected, observed/expected ratio (o/e) 0.49, 90% interval 0.32 to 0.76. The upper end of that interval is the gene's LOEUF score, 0.76, which puts it in group 3 of 6, group 1 being the genes least tolerant of losing a copy. Missense variants: 294 observed, 344.55 expected, observed/expected ratio (o/e) 0.85, 90% interval 0.77 to 0.94. Synonymous variants: 139 observed, 134.48 expected, observed/expected ratio (o/e) 1.03, 90% interval 0.9 to 1.19.
Homologues: Orthologues: macaque CCNY (100% identical), dog CCNY (99% identical), guinea pig CCNY (99% identical), mouse Ccny (98% identical), pig CCNY (98% identical), rat Ccny (98% identical), tropical clawed frog ccny (93% identical), zebrafish ccny (91% identical), chimpanzee CCNY (88% identical), rabbit CCNY (86% identical), Drosophila melanogaster CycY (65% identical), Caenorhabditis elegans cyy-1 (55% identical). Paralogues in human: CCNYL1 (74% identical), CCNYL1B (44% identical).
Diseases named in the same sentence as CCNY in open-access papers:
CCNY is named in the same sentence as 31 diseases in open-access papers, as found by Europe PMC text mining. Sharing a sentence is not in itself a finding about the gene and the disease. The quoted sentences say what the papers report.
hepatocellular carcinoma (6 papers, 2015 to 2025). A malignant tumor that arises from hepatocytes. "Particularly, CCNY was highly expressed in human cancers, such as hepatocellular carcinoma (HCC) cells, lung cancer tissues and cell lines, glioma cells, and colorectal carcinoma cell lines." (PMID 34222253, 2021). "In contrast, our data from HCT116 cells suggest that cyclin Y is uncoupled from LRP6 phosphorylation and Wnt signaling in intestinal epithelia, a phenomenon that has also been observed in hepatocellular carcinoma cells." (PMID 34571979, 2021). "As reported in hepatocellular cancer, PFTK1 and/or CCNY alone could activate non-canonical Wnt signaling causing cells migration and invasion." (PMID 26488471, 2015).
breast carcinoma (4 papers, 2019 to 2025). "In breast cancer cells, phosphorylation of PRC1 by the CDK16/CCNY complex has been linked to accelerated cell cycle progression and tumor growth." (PMID 40665337, 2025). "The oncogenic role of CCNY has been reported in various cancers, including breast cancer, suggesting the potential function of CCNY-dependent CDKs in cancer progression." (PMID 35449080, 2022). "Ccnys have been reported to regulate mammary stem cell activity and mammary gland development, and CCNY has been recognized as an oncoprotein in various cancers, including breast cancer." (PMID 35449080, 2022). "In this study, we sought to reveal a novel therapeutic target for breast cancer among CCNY-dependent CDKs by clinical correlation analysis and functional study." (PMID 35449080, 2022). "In many tumors, CCNY was involved in regulating cell growth, such as in HCC, renal cancer, breast cancer, and ovarian cancer." (PMID 34222253, 2021).
lung carcinoma (4 papers, 2015 to 2025). "The results of the Kaplan-Meier survival analysis demonstrated a significant association between high Cyclin Y expression and decreased overall survival in lung cancer patients." (PMID 40083692, 2025). "To elucidate the mechanisms underlying the regulatory role of Cyclin Y in lung cancer, we conducted an RNA-seq analysis utilizing A549 cells that were transfected with control or Cyclin Y siRNAs and revealed numerous downstream genes with altered expression patterns." (PMID 40083692, 2025). "Conversely, the overexpression of Cyclin Y facilitated the growth and proliferation of lung cancer cells." (PMID 40083692, 2025). "Our findings provide novel insights into the biological significance of Cyclin Y in lung cancer radioresistance." (PMID 40083692, 2025). "Conversely, RRM2 overexpression partially reversed the inhibitory effects on cell growth and proliferation induced by Cyclin Y depletion in lung cancer cells." (PMID 40083692, 2025). "Suppression of Cyclin Y was found to induce DNA damage and impair DNA repair, consequently augmenting the radiosensitivity of lung cancer cells." (PMID 40083692, 2025). "In this study, we reveal that Cyclin Y is overexpressed and that Cyclin Y silencing suppresses lung cancer cell proliferation and enhances radiosensitivity both in vitro and in vivo." (PMID 40083692, 2025). "To explore the expression of Cyclin Y in lung cancer and its potential prognostic significance, we performed western blot analysis on several lung cancer cell lines." (PMID 40083692, 2025). "The knockdown of Cyclin Y resulted in significant inhibition of lung cancer cell growth and proliferation." (PMID 40083692, 2025). "In our study, we found that Cyclin Y exhibits elevated expression levels in lung cancer tissues, which is strongly correlated with an unfavorable prognosis." (PMID 40083692, 2025). "Rescue experiments confirm that the effects of Cyclin Y on lung cancer are mediated partially by RRM2." (PMID 40083692, 2025). "Taken together, these results demonstrate that the depletion of Cyclin Y in lung cancer cells results in an increase in residual DNA damage and an impairment in DNA damage repair following irradiation." (PMID 40083692, 2025). "Furthermore, we identify RRM2 as a crucial downstream effector of Cyclin Y involved in the biological processes associated with Cyclin Y. These findings suggest that targeting Cyclin Y could serve as a promising approach for enhancing the efficacy of radiotherapy in lung cancer treatment." (PMID 40083692, 2025). "Using clonogenic survival assays, we demonstrated that depletion of Cyclin Y resulted in increased radiosensitivity in lung cancer cell lines." (PMID 40083692, 2025). "In our study, we found that two isoforms of CCNY with different subcellular distributions were highly expressed in lung cancer cells and NSCLC tissues." (PMID 34222253, 2021). "Our immunoblotting results indicated that CCNY level was much higher in lung cancer cells than that in MRC5 cells." (PMID 34222253, 2021). "Two bands for different molecular weights (MWs) (32 and 39 kD) were detected, indicating that different isoforms of CCNY were selectively expressed in different lung cancer cells." (PMID 34222253, 2021). "In order to identify the localization of CCNY isoforms, cytoplasmic extracts, membrane extracts and nuclear extracts of lung cancers were collected, respectively." (PMID 34222253, 2021). "Lung cancer TMAs were used to study the expression of CCNY in NSCLC tissues; CCNYc was highly expressed in lung cancer tissues." (PMID 34222253, 2021). "In our research, we pointed out that CCNY was mainly localized in the cell cytoplasm in most of the lung cancer cells and NSCLC tissues." (PMID 34222253, 2021). "In this study, the subcellular location of CCNY in lung cancer tissues and cells was detected by immunofluorescence assay (IF), Western blot (WB), and immunohistochemistry (IHC)." (PMID 34222253, 2021).
lung carcinoma (continued). "The role of CCNYc in lung cancer cells was explored using H1299 and 95D cells, in which CCNY was only sublocalized in the cell cytoplasm." (PMID 34222253, 2021). "In glioma and lung cancer cells, knockdown of CCNY inhibits cell proliferation and overexpression of CCNY promotes cell proliferation." (PMID 26220330, 2015). "In summary, our study is the first to reveal the role of Cyclin Y in lung cancer radioresistance." (PMID 40083692, 2025). "However, the function and regulatory mechanism of Cyclin Y in lung cancer radioresistance remain poorly understood." (PMID 40083692, 2025). "However, the role and regulatory mechanism of Cyclin Y in lung cancer radiotherapy have yet to be elucidated." (PMID 40083692, 2025). "Furthermore, we demonstrated that Cyclin Y depletion suppresses lung cancer progression both in vitro and in vivo." (PMID 40083692, 2025). "Moreover, we showed that exogenously expressed Cyclin Y formed a complex with exogenous or endogenous Chk1 in lung cancer cells." (PMID 40083692, 2025). "Notably, we demonstrate that the biological effects caused by Cyclin Y knockdown can be partially rescued by RRM2, highlighting the significance of the Cyclin Y/RRM2 axis in the regulation of lung cancer progression and radiosensitivity." (PMID 40083692, 2025). "Based on the observed elevated expression of Cyclin Y and its potential prognostic implications, we hypothesized that Cyclin Y plays an oncogenic role in lung cancer." (PMID 40083692, 2025). "Additionally, immunohistochemical staining of lung adenocarcinoma tissue microarrays, consisting of 90 paired cancerous and paracancerous tissues, exhibited elevated levels of Cyclin Y protein expression in lung cancer tissues." (PMID 40083692, 2025). "In this study, it demonstrated that CCNY was highly expressed in lung cancer." (PMID 34222253, 2021). "In lung cancer cells, CCNY was mainly localized in the cytoplasm." (PMID 34222253, 2021). "The distributions of CCNY in lung cancer cells were also detected by immunofluorescence assay." (PMID 34222253, 2021). "In lung cancer cells we detected, CCNY was mainly localized in the cytoplasm." (PMID 34222253, 2021). "In lung cancer tissue, CCNY was also mostly localized in the cytoplasm except for one case." (PMID 34222253, 2021). "Importantly, we revealed the previously unknown role of Cyclin Y in promoting radioresistance in lung cancer." (PMID 40083692, 2025). "The CCNY/PFTK1 complex may also play important roles in lung cancer." (PMID 34222253, 2021). "Moreover, CCNY was mainly localized in the cell cytoplasm of lung cancer." (PMID 34222253, 2021). "Cyclin Y interacts with Chk1, thereby activating the RRM2/STAT3 signaling pathway and promoting radioresistance in lung cancer." (PMID 40083692, 2025). "IF assay was also used to detect the distribution of endogenous CCNY and PFTK1 in lung cancer cells." (PMID 34222253, 2021). "Median protein expression of CCNY, CCNO, CCNI, and CNTD2 was higher in lung cancer than normal lung tissue, but statistical significance was only found for CCNI and CNTD2." (PMID 28860486, 2017). "Importantly, we demonstrate that Cyclin Y interacts with Chk1 to positively modulate the expression of RRM2 and activate STAT3 signaling, ultimately promoting radioresistance in lung cancer." (PMID 40083692, 2025). "Consequently, the endogenous CCNY and PFTK1 are located in the same subcellular compartments in lung cancer cells." (PMID 34222253, 2021). "Collectively, we reveal for the first time that Cyclin Y promotes lung cancer radioresistance by binding to Chk1 to activate RRM2/STAT3 signaling, indicating that targeting Cyclin Y may be a promising strategy for enhancing the efficacy of radiotherapy in the treatment of non-small cell lung cancer." (PMID 40083692, 2025). "Notably, depletion of Cyclin Y did not lead to significant changes in the cell cycle distribution or DNA damage levels in the absence of irradiation in lung cancer cells." (PMID 40083692, 2025).
glioma (3 papers, 2015 to 2021). A benign or malignant brain and spinal cord tumor that arises from glial cells (astrocytes, oligodendrocytes, ependymal cells). "Cell growth ability was inhibited by suppressing CCNY expression in glioma cells and HCC." (PMID 34222253, 2021).
renal carcinoma (3 papers, 2019 to 2023). A carcinoma arising from the epithelium of the renal parenchyma or the renal pelvis. "Therefore, we suggest that fisetin inhibition of mitosis in renal cancer stem cells is achieved through inhibition of CCNY and CDK16 expression." (PMID 30411496, 2019). "Through molecular biology experiments, we found that the mRNA and protein expression levels of endogenous CCNY and CDK16 were significantly decreased in fisetin‐treated renal cancer stem cells." (PMID 30411496, 2019). "Therefore, in summary, we found that fisetin inhibits the epigenetic mechanism in renal cancer stem cells, that is, fisetin inhibits TET1 expression and reduces 5hmC modification in specific loci in the promoters of CCNY/CDK16 in renal cancer stem cells." (PMID 30411496, 2019). "Thus, we conclude that fisetin inhibits the epigenetic mechanism in renal cancer stem cells, that is, fisetin inhibits TET1 expression and reduces 5hmC modification in specific loci in the promoters of CCNY/CDK16 in HuRSCs." (PMID 30411496, 2019).
colon cancer (2 papers, 2021). "Whereas expression levels of CCNY, CCNYL1, and CDK16 were broadly comparable across all cell types, the average level of CDK14 was more than an order of magnitude lower in colon cancer cells compared to any other tissue included in this analysis." (PMID 34571979, 2021).
colorectal cancer (2 papers, 2018 to 2021). A primary or metastatic malignant neoplasm that affects the colon or rectum. "Importantly, although HCT116 are colorectal cancer cells that harbor an activating mutation in β-catenin, they respond to Wnt ligands by LRP6 activation and increased proliferation, making them a suitable model for studying cyclin Y biology." (PMID 34571979, 2021).
diabetes (2 papers, 2015 to 2016). "Together, these results provide a new link between CCNY and lipid metabolism in mice, and suggest that inhibition of CCNY may offer a therapeutic approach to obesity and diabetes." (PMID 26161966, 2015).
inflammatory bowel disease (2 papers, 2020 to 2021). A spectrum of small and large bowel inflammatory diseases of unknown etiology. "The CCNY gene, which encodes cyclin Y, has been implicated in the pathogenesis of inflammatory bowel disease (IBD)." (PMID 34571979, 2021).
ovarian carcinoma (2 papers, 2012 to 2021). A malignant neoplasm originating from the surface ovarian epithelium. "In HCC and ovarian cancer, CCNY also promoted cell migration and invasion." (PMID 34222253, 2021).
colitis (1 paper, 2021). Inflammation of the colon. "We conclude that cyclin Y is dispensable for intestinal epithelial homeostasis and wound repair in experimental colitis." (PMID 34571979, 2021). "Cyclin Y promotes Wnt/β-catenin signaling and autophagy, which are critical for intestinal epithelial cell (IEC) homeostasis, and may thereby contribute to wound repair in colitis." (PMID 34571979, 2021).
diarrheal disease (1 paper, 2025). The condition of having at least three loose or liquid bowel movements each day. "The discovery that our identified CREM locus reference allele was associated with alterations in CREM-regulated gene expression but not changes in CCNY or CUL2 mRNA enabled us to ascribe the CREM locus reference allele phenotypes affecting diarrheal disease and undernutrition to CREM itself." (PMID 40576353, 2025).
Intellectual disability (1 paper, 2015). "We also report that recently identified PCTAIRE-1 variants found in patients with intellectual disability were unable to interact with cyclin Y and are inactive enzymes." (PMID 26205494, 2015). "Finally, we observed that recently identified PCTAIRE-1 variants found in patients with intellectual disability were unable to interact with cyclin Y, and were inactive enzymes." (PMID 26205494, 2015).
lymph node metastasis (1 paper, 2025). "Further analysis of the correlations between these molecules and patient characteristics demonstrated that the staining intensities of phosphorylated PRC1 and CCNY were linked to advanced stages, lymph node metastasis, and distant metastasis in patients." (PMID 40665337, 2025).
male infertility (1 paper, 2015). The inability of the male to effect fertilization of an ovum after a specified period of unprotected intercourse. "It has been reported that conditional knockout of Cdk16 in mice leads to male infertility; CDK16 protein interacts with CCNY protein, and CCNY is highly expressed in the testis in comparison with its levels in the brain and heart." (PMID 26305884, 2015).
medulloblastoma (1 paper, 2020). A malignant, invasive embryonal neoplasm arising from the cerebellum. "Interestingly, the fraction of M2 macrophages in Group 4 medulloblastoma were positively correlated with the risk score and were significantly correlated with the expression level of four signature genes (CCNY, SYNE3, CYB5D2, and SELENOV) and four hub genes (GLI2, PAX6, RUNX2, and ZIC1)." (PMID 32508873, 2020).
non-small cell lung carcinoma (1 paper, 2025). A group of at least three distinct histological types of lung cancer, including non-small cell squamous cell carcinoma, adenocarcinoma, and large cell carcinoma. "In this study, we present evidence demonstrating that Cyclin Y is overproduced and that Cyclin Y silencing impairs tumorigenesis and radioresistance in non-small cell lung cancer in vitro and in vivo." (PMID 40083692, 2025). "Our research not only provides partial insight into the mechanism by which Cyclin Y functions, but also suggests that targeting Cyclin Y represents a promising approach for enhancing the sensitivity of non-small cell lung cancer to radiotherapy." (PMID 40083692, 2025). "In this study, we find that Cyclin Y is overexpressed in non-small cell lung cancer and correlates with poor prognosis." (PMID 40083692, 2025).
ovarian tumours (1 paper, 2012). "We next looked for co-expression of CCNY/CREM in our previous analysis of ovarian tumours." (PMID 22514011, 2012).
pulmonary disorder (1 paper, 2022). "Based on pathway enrichment analysis, genes altered in BPD blood cells were mainly enriched in cell cycle regulation and arrest (e.g., PPP2CA, RBL2, CENPU, CCNY, CDK6) and pulmonary disorder and developmental disorders (e.g., AGER, ITGA6, CA4, BACH2, IGFBP2, BMPR2, SKI, DAB2)." (PMID 35484630, 2022).
triple-negative breast carcinoma (1 paper, 2023). An invasive breast carcinoma which is negative for expression of estrogen receptor (ER), progesterone receptor (PR), and human epidermal growth factor receptor 2 (HER2). "In triple-negative breast cancer, the CDK14/CCNY complex phosphorylates the membrane receptor LRP6 and regulates the activity of breast cancer stem cells through the Wnt/β-catenin signaling pathway, ultimately promoting the progression and metastasis of triple-negative breast cancer." (PMID 37599359, 2023).
type 2 diabetes (1 paper, 2020). "In the present study, CCNY was discovered by a proteomic study that was initially aimed to identify proteins that are differentially expressed in platelets from healthy donors and from patients with type 2 diabetes." (PMID 33153214, 2020).